PPARA (peroxisome proliferator activated receptor alpha)
Diseases named in the same sentence as PPARA in open-access papers (continued):
Sharing a sentence is not in itself a finding about the gene and the disease.
diabetic cardiomyopathy (54 papers, 2008 to 2026). Diabetic cardiomyopathy is a disorder of the heart muscle in people with diabetes. "Increases in PPARα activity have also been linked to diabetic cardiomyopathy via causing a lipotoxicity associated with increased fatty acid storage and oxidation, whereas exendin-4 failed to improve the mitral E/A ratio in mice with T2DM and a cardiac-restricted overexpression of PPARα." (PMID 33364978, 2020). "Interestingly, the overexpression of PPARα in cardiomyocytes alone is sufficient to phenocopy many of the features of this cardiomyopathy, while PPARα deficiency is protective against a streptozotocin-induced model of diabetic cardiomyopathy." (PMID 29408889, 2018). "Conversely, PPARα deficiency is protective in models of diabetic cardiomyopathy." (PMID 25815008, 2015). "In contrast, diabetic cardiomyopathy is characterized by sustained PPARα activation, promoting excessive fatty acid oxidation, lipid accumulation and lipotoxicity." (PMID 42193950, 2026). "Conversely, in diabetic cardiomyopathy models, PPARA activation increases the expression of genes related to β-oxidation, which generates reactive oxygen species (ROS) and contributes to heart dysfunction and mitochondrial damage." (PMID 41373582, 2025). "ERRγ can control the expression of PPARα, suggesting a potential ERRγ–PPARα axis for reprograming the metabolic profile in diabetic cardiomyopathy." (PMID 34831481, 2021). "MiR-30c prevented diabetic cardiomyopathy by reducing the peroxisome proliferator-activated receptor alpha level." (PMID 33817282, 2020). "Our results provide the first direct evidence that GLP‐1 protects cardiac function by inhibiting the ROCK/PPARα pathway, thereby ameliorating lipotoxicity in diabetic cardiomyopathy." (PMID 29659121, 2018). "Cardiac PPARα, PPARβ, and PPARγ1 have pivotal roles in the pathophysiology of diabetic cardiomyopathy." (PMID 26242235, 2015). "MuRF3 is identified as an ubiquitin ligase that mono-ubiquitinates cardiac PPARα and PPARγ1 activities in vivo via post-translational modification, which appears to support PPAR stability in the context of diabetic cardiomyopathy." (PMID 26215257, 2015). "Activation of myocardial PPARα regulatory pathway mainly contribute to the pathogenesis of diabetic cardiomyopathy." (PMID 23049681, 2012). "Moreover, overexpression of the PPARα gene in the hearts of diabetic mice has been related to both cardiac dysfunction and diabetic cardiomyopathy (DCM) development." (PMID 37048208, 2023). "Overall, these data suggest that decreased cardiac PPARα reduces cardiac lipid accumulation in the heart, and could potentially protect against diseases with dysregulated lipid storage such as diabetic cardiomyopathy." (PMID 35259201, 2022). "In summary, exendin‐4 protected against diabetes cardiomyopathy via a PPARα mechanism." (PMID 29659121, 2018). "Indeed, cardiac overexpression of PPARα confers a phenotype that has many of the features of a diabetic cardiomyopathy." (PMID 25815008, 2015). "Therefore, the PPARα mediated lipotoxic cardiomyopathy is one of the important mechanisms in the pathogenesis of diabetic cardiomyopathy." (PMID 23049681, 2012). "To this end, we found that therapy with APS could well reverse the PPARα-mediated myocardial lipotoxicity in the pathogenesis of diabetic cardiomyopathy." (PMID 23049681, 2012). "We conclude that APS therapy could prevent the development of diabetic cardiomyopathy through a mechanism mainly dependent on the cardiac PPARα-mediated regulatory pathways." (PMID 23049681, 2012). "To further explore the potential mechanism, we throw the hypothesis that APS may improve diabetic cardiomyopathy with the inhibition of myocardial lipotoxicity dependent on the cardiac PPARα regulatory pathway." (PMID 23049681, 2012).
diabetic cardiomyopathy (continued). "More importantly, cardiac ischemia–reperfusion injury with enhanced fatty acid oxidation was ameliorated after silencing of the PPARα pathway in mice with impaired BCAA metabolism, suggesting that PPARα may be a downstream pathway of BCAA metabolism leading to diabetic cardiomyopathy." (PMID 35911554, 2022). "At a molecular level, PPARα is thought to be a key mediator of these metabolic alterations, as both T1D and T2D lead to increases in myocardial PPARα expression, and cardiac-specific PPARα overexpressing mice exhibit a cardiac phenotype mimicking that seen in diabetic cardiomyopathy." (PMID 33041869, 2020). "Indeed, cardiac overexpression of PPARα mimics diabetic cardiomyopathy." (PMID 30061171, 2018). "Silencing peroxisome proliferator-activated receptor alpha reduces HMGCS2 expression and alleviates myocardial injury in diabetic cardiomyopathy." (PMID 40361044, 2025). "The pathogenesis of diabetic cardiomyopathy involves the enhanced activation of PPAR transcription factors, including PPARα, and to a lesser degree PPARβ and PPARγ1." (PMID 26242235, 2015). "We identified that MuRF2−/− hearts undergo an exaggerated diabetic cardiomyopathy, resulting from MuRF2’s multi-ubiquitination of PPARα and PPARγ1 in a proteasome-independent (non-degradatory) mechanism." (PMID 26242235, 2015). "The pathogenesis of diabetic cardiomyopathy (DCM) involves the enhanced activation of peroxisome proliferator activating receptor (PPAR) transcription factors, including the most prominent isoform in the heart, PPARα." (PMID 26215257, 2015). "Mechanistically, MuRF2 mono-ubiquitinated PPARα and PPARγ1 in vitro, consistent with its non-degradatory role in diabetic cardiomyopathy." (PMID 26242235, 2015). "Morever, the energy metabolism signaling pathway of PPARα-FFA in cardiomyocytes may joint with ventricular remodeling, which are important reasons for the pathogenesis of diabetic cardiomyopathy." (PMID 26281830, 2015). "PPARα and PPARβ/δ direct distinct metabolic regulatory programs and PPARα mice develop lipotoxic cardiomyopathy which resembles the diabetic cardiomyopathy whereas PPARβ/δ mice do not." (PMID 20628611, 2010).
diabetic nephropathy (52 papers, 2008 to 2025). "All three members of the PPAR subfamily, PPARα, PPARβ/δ, and PPARγ, have been implicated in many renal pathophysiological conditions, including acute kidney injury, diabetic nephropathy, and chronic kidney disease, among others." (PMID 35308207, 2022). "PPARα deficiency appears to aggravate the severity of diabetic nephropathy through an increase in extracellular matrix formation, inflammation, and circulating free fatty acid and triglyceride concentrations." (PMID 26821914, 2016). "We have previously reported that PPARα deficiency appears to aggravate the severity of diabetic nephropathy through increase in extracelluar matrix formation, inflammation and circulating FFA and TG concentrations." (PMID 24801481, 2014). "This study demonstrates that diabetic nephropathy is associated with an increase in renal lipid accumulation, apoptotic renal injury and oxidative stress which are related to a decreased level of PPARα expression in diabetic mice." (PMID 24801481, 2014). "Over and above their effects on lipid metabolism, PPARα agonists also appear to have direct effects on a number of critical pathways that are implicated in the development and progression of diabetic kidney disease." (PMID 22448165, 2012). "Importantly, ablation of PPARα in mice leads to an increased susceptibility to diabetic nephropathy and exacerbated free fatty acid-induced injury in the kidney." (PMID 27463191, 2016). "In addition, the PPARα agonists gemfibrozil and fenofibrate were able to reduce kidney hypertrophy and fibrosis associated with diabetic nephropathy in two different diabetic animal models." (PMID 21311715, 2011). "The involvement of PPARα-mediated FAO has been implicated in various renal conditions, such as acute kidney injury, diabetic nephropathy, and chronic kidney disease." (PMID 40556756, 2025). "PPARα-null mice treated with streptozotocin (STZ) exhibit accelerated diabetic nephropathy, including worsened albuminuria, glomerular sclerosis, mesangial matrix expansion, collagen deposition, and macrophage infiltration." (PMID 40717128, 2025). "PPARα agonists have been studied as potential treatments for diabetic nephropathy (DN) in rodents, with evidence supporting their renoprotective effects." (PMID 40717128, 2025). "In diabetic kidney disease mice, increased expression of PPARα was confirmed to be effective in increasing the expression of downstream proteins involved in fatty acid oxidation, restoring renal function, and suppressing fibrosis in vitro and in vivo." (PMID 41020857, 2025). "Studies have shown that the PPARα agonist Fenofibrate can improve renal function by inhibiting the oxidative stress, inflammatory response, and apoptosis in diabetic nephropathy rats." (PMID 34262471, 2021). "As classical PPARα agonists, fibrates reportedly suppress microalbuminuria in patients with diabetic nephropathy." (PMID 34207854, 2021). "It has been reported that the expression of PPARα in kidney tissue is downregulated in the mouse model of high-fat diet and cases of stage IV of diabetic nephropathy, which is inconsistent with our results." (PMID 31097920, 2019). "Although several NHRs, including peroxisome proliferator-activated receptor-γ (PPARγ) and PPARα, demonstrate a renoprotective effect in the context of diabetic nephropathy (DN), the expression and role of other NHRs in the kidney are still unrecognized." (PMID 24465611, 2014). "Fenofibrate, a PPARα agonist, has been shown to attenuate extracellular matrix formation in diabetic nephropathy." (PMID 24130796, 2013). "For example, PPARα agonists are also able to increase gene expression of the key slit-pore protein, nephrin, in diabetic nephropathy, potentially contributing to their antiproteinuric actions." (PMID 22448165, 2012). "By contrast, in diabetic PPARα-knockout mice, diabetic nephropathy is more severe than in wild-type mice." (PMID 22448165, 2012).
diabetic nephropathy (continued). "Although the abundance of PPARα in the kidney is well established, its role in renal physiology and diabetic nephropathy is just emerging." (PMID 21076544, 2010). "Further evidence fromboth clinical and experimental studies is necessary to clarify the therapeutic potentialof PPARβ/δ and PPARα agonists in diabetic nephropathy." (PMID 19277201, 2008). "The study clarified the mechanism of the ZGP and YGP by regulating the transcriptional regulatory network of HIF1A and PPARA and provided new ideas for the discovery of potential targets for the treatment of diabetic nephropathy and the development of natural nutrients." (PMID 40417738, 2025). "Additionally, PDK4, a downstream gene of PPARA, was identified as a potential key node in the gene co‐expression network of diabetic nephropathy." (PMID 40417738, 2025). "PPARα has also been recently found to play roles in progress of diabetic nephropathy (DN)." (PMID 36589809, 2022). "For example, fenofibrate, a PPARα agonist that is currently utilized for the treatment of hypertriglyceridemia, is currently being evaluated in a phase 3 trial for the treatment of patients with diabetic kidney disease (NCT03869931)." (PMID 34442464, 2021). "The activation of PPARα was reported to improve diabetic nephropathy in db/db mice." (PMID 34262471, 2021). "Although human data revealed that fibrates improve diabetic nephropathy such as albuminuria, data from rodent studies demonstrate more effectiveness than those of clinical studies, suggesting that rodents are more sensitive to PPARα signaling." (PMID 32226789, 2020). "On the other hand, it seems that PPARα activation impedes the progression of diabetic nephropathy." (PMID 32226789, 2020). "Several metabolic experimental studies, including murine studies employing a high-fat-diet-induced glomerular injury model or a diabetic nephropathy model, have also demonstrated the beneficial properties of the PPARα agonist fibrates in reducing glomerular lesions." (PMID 22675338, 2012). "PPARα agonists exert a range of anti-inflammatory actions which may be beneficial in diabetic kidney disease." (PMID 22448165, 2012). "The PPARα agonist fenofibrate prevents diabetic nephropathy in db/db mice." (PMID 19609456, 2009). "PPARα agonists may, therefore, decrease lipotoxicityand, consequently, inhibit the progression of diabetic nephropathy." (PMID 19277201, 2008). "Indeed, all three PPAR subtypes share common lipid-lowering properties, and PPARα and PPARγ exert similar renoprotective effects in animals or humans with diabetic nephropathy." (PMID 20671947, 2010). "Thus, both PPARβ/δ and PPARα agonists could be implemented in newtherapeutic strategies designed to prevent diabetic nephropathy by reducingrenal lipotoxicity." (PMID 19277201, 2008). "In the present study, we elucidated the novel anti‐diabetic nephropathy mechanism of ZGP and YGP through PPARA and HIF1A transcriptional regulatory networks and their specific downstream genes CA9, PDK1, and PDK4." (PMID 40417738, 2025). "HIF1A, PPARA, and SREBF1 were key transcriptional factors for the treatment of diabetic nephropathy by EZP and EYP in renal function." (PMID 40417738, 2025). "This study proposed a novel perspective for the treatment of diabetic nephropathy by analyzing the mechanisms of ZGP and YGP through the transcriptional regulatory networks of PPARA and HIF1A." (PMID 40417738, 2025). "CA9 and PDK1, the downstream genes of HIF1A, and PDK4, the downstream gene of PPARA, were activated by both EZP and EYP, which showed the potential new targets of diabetic nephropathy." (PMID 40417738, 2025). "Compared to the strongly positive signal in normal kidneys, CPT1A and PPARα were decreased in kidney biopsies from patients with CKD, including IgAN, membranous nephropathy (MN), lupus nephritis (LN) and diabetic nephropathy (DN)." (PMID 39438470, 2024).
diabetic nephropathy (continued). "Bailing Capsule activated the expression of PPARα, ACOX1 (acyl-CoA oxidase 1), and SCD (stearoyl-CoA desaturase) in diabetic nephropathy while suppressing the expression of FASN (fatty acid synthase)." (PMID 36091833, 2022). "Resveratrol prevents diabetic nephropathy via the following mechanism: resveratrol activates the AMPK-SIRT1-PGC-1alpha axis and PPARα by increasing AdipoR1 and AdipoR2 expression and prevents high glucose-induced oxidative stress and cell apoptosis." (PMID 32065783, 2020). "PPARA is a well‐established target for regulating glucose and lipid metabolism, suggesting that EZP and EYP share a common mechanism for modulating glucose and lipid metabolism in diabetic nephropathy." (PMID 40417738, 2025). "It was also shown that the overexpression of PPARα has a renoprotective effect by upregulating the FAO pathway, which suggests that this may also be involved in the development of diabetic nephropathy." (PMID 41020857, 2025). "Studies have reported that AdipoRon may be a promising agent to treat diabetic nephropathy by stimulating intracellular calcium ions, activating the AMPK-LKB1/PPARα signaling pathway, and increasing ceramidase activity via activation of AdipoRs and downstream targets." (PMID 32065783, 2020). "However, PPARA agonists and PDK4 mediators have not been widely utilized in the clinical treatment of diabetic nephropathy." (PMID 40417738, 2025).
renal fibrosis (46 papers, 2015 to 2026). A final common manifestation of a wide variety of chronic kidney diseases characterized by glomerulosclerosis and tubulointerstitial fibrosis. "Impaired PPARα and Acox1 activity have been implicated in age-associated renal fibrosis and can be reversed through calorie restriction." (PMID 35222262, 2021). "Another evidence that links the derangement of FAO to fibrosis is the progressive decrease of the expression of peroxisome proliferator-activated receptor α (PPARα) in aged people, that triggers the age-associated renal fibrosis." (PMID 32733282, 2020). "Similarly, our previous study also demonstrated an impairment of PPARα in the regulation of age-associated renal fibrosis in aged PPARα−/− mouse models." (PMID 34639224, 2021). "In conclusion, lactate disrupts renal lipid homeostasis and exacerbates renal fibrosis by inhibiting the PPARα/FAO pathway." (PMID 41808346, 2026). "Fenofibrate mitigated renal fibrosis and prevented cell death by increasing PPARα in rat models of DKD." (PMID 40303925, 2025). "In renal fibrosis, exercise regulates key molecules in lipid metabolism (such as PPARα) and the renin-angiotensin system, reducing lipid accumulation and slowing the progression of fibrosis." (PMID 40182630, 2025). "PPARα activator MHY2013 significantly reduced lipid accumulation in TECs and attenuated renal fibrosis in senescent rats, which further emphasized the importance of PPAR α and FAO in regulating renal lipid homeostasis." (PMID 38910210, 2024). "MiR-21 promotes renal fibrosis by downregulating antifibrotic genes, including peroxisome proliferator-activated receptor alpha (PPAR-α), which leads to fibrotic processes." (PMID 39728069, 2024). "STAT6 contributes to renal fibrosis by interacting with the PPARα promoter, suppressing FAO, and supporting MMT." (PMID 39445007, 2024). "In summary, our findings first uncovered the key role of CXCR4 in regulating PPARα‐mediated fatty acid oxidation and renal tubular cell senescence‐related renal fibrosis through activating β‐catenin signalling." (PMID 38213100, 2024). "The expression of miR-21, an miRNA known to inhibit PPARα translation, was substantially upregulated, and the ablation of PPARα triggered an accumulation of renal lipids and the deterioration of renal fibrosis." (PMID 38069234, 2023). "Proximal tubule PPARα and PPARGC1a attenuates renal fibrosis and inflammation induced by UUO and other injuries." (PMID 37032786, 2023). "STAT6 inhibition promotes a shift to FAO for energy utilization by inducing PPARα activation in tubular cells, thereby attenuating the lipid accumulation and alleviating renal fibrosis." (PMID 36685533, 2022). "Fenofibrate is a well-known PPARα agonist which has been reported to significantly improve renal fibrosis." (PMID 35455432, 2022). "PPARα levels are decreased in a unilateral ureteral obstruction (UUO) rat model 8, and PPARα signaling is disrupted in aging kidney during accelerated renal fibrosis." (PMID 36147466, 2022). "One study found PPARα levels are decreased in a UUO rat model 8, while another investigation showed damaged PPARα signaling in aging kidney during accelerated renal fibrosis." (PMID 36147466, 2022). "Consistent with the reports, our study showed that the gene expression of FAO-related key metabolic enzymes (CPT1A, CPT2, and ACOX2) and the FAO transcription regulatory factors (PPARα and PGC1α) were markedly decreased in renal fibrosis induced by I/R." (PMID 35526054, 2022). "The strong correlations between FAO transcripts, urinary nicotinamide metabolites, and urinary TCA cycle intermediates with mitochondrial roundness links increased PPARα activity after RYGB-FMRR with mitochondrial bioenergetic changes opposing renal fibrosis." (PMID 35222262, 2021). "Fenofibrate treatment restores tubular FAO via PPARα agonism and reduces renal fibrosis in experimental models." (PMID 35222262, 2021).